CASP1 (caspase 1)
Diseases named in the same sentence as CASP1 in open-access papers (continued):
Sharing a sentence is not in itself a finding about the gene and the disease.
bacterial infection (67 papers, 2010 to 2025). "Upregulated IL-6 caused by bacterial infection inhibited caspase-1/-3 activation to suppress GSDMD-/GSDME-mediated pyroptosis and played a partially protective role." (PMID 38022612, 2023). "Its underlying mechanism involves the activation of caspase-1 and its related inflammasomes such as caspase-11, which lead to host defense against bacterial infections." (PMID 33579316, 2021). "Bacterial infections were shown to trigger caspase-1 associated pyroptosis and TNF-induced necrosis (Blériot and Lecuit, 2016)." (PMID 30280094, 2018). "The key factors in the activation of caspase-1 in bacterial infection are mainly pore-forming toxins or virulence-associated secretion systems." (PMID 23357873, 2013). "Moreover, gene activation of inflammasome associated components such as NLRP1, ASC and caspase-1 has been described in response to bacterial infection in zebrafish (Danio rerio) and turbot (Scophthalmus maximus)." (PMID 33676414, 2021). "Since pore-forming toxins or virulence-associated secretion systems in bacterial infection mediate caspase-1 activation, we considered the possibility that V. parahaemolyticus might induce caspase-1 activation." (PMID 23357873, 2013). "Additionally, mouse JAX phenotypes for CASP1 show both increased and decreased susceptibility to bacterial infection, as well as decreased inflammatory response." (PMID 22432004, 2012). "Conversely, the downregulation of CCL4 and CCL25 in caspase-1-deficient cells suggests that caspase-1 is essential for maintaining adequate recruitment of macrophages and dendritic cells, which are important for mounting an effective immune response against bacterial infections." (PMID 40137780, 2025). "As caspase-1 and IL-1β have previously been associated with resistance to bacterial infections and are also linked to macrophage killing of B. anthracis, we hypothesized that the LT-dependent IL-1β response in Nlrp1bS-expressing mice might explain their relative resistance." (PMID 21170303, 2010). "By delivering LPS into the cytoplasm and binding to cellular receptors, OMVs initiate caspase-1 activation and cellular pyroptosis, underscoring the pivotal role of OMVs in bacterial infection." (PMID 40568700, 2025). "Recently, Liu and co-workers tagged tetraphenylethylene (TPE) moiety with a casp-1 cleavable protein to image bacterial infection under the microscope." (PMID 40136927, 2025). "Casp-1 is produced upon bacterial infection and cleaves the NEAYVHDAP sequence of peptide-tagged TPE to trigger AIE of TPE." (PMID 40136927, 2025). "YopM, a crucial factor for Yersinia’sability to cause disease, has been shown to directly attach to caspase-1 and prevent its activation, which effectively hinders caspase-1-dependent pyroptosis and facilitates bacterial infection in vivo." (PMID 40593504, 2025). "In conjunction with previous studies, IL-22 has been shown to inhibit the activation of the NLRP3 inflammasome by suppressing the synthesis of NLRP3 and Caspase-1 proteins, thereby attenuating mammalian bacterial diseases and tissue injury." (PMID 39211040, 2024). "Caspase-1 is critical for inflammasome-dependent cytokine release and pyroptosis during bacterial infection, and is activated during Y. enterocolitica infection of Caco-2 cells." (PMID 37615436, 2023). "Up-regulated IL-6 caused by bacterial infection inhibited GSDMD/GSDME-mediated pyroptosis by suppressing caspase-1/3 activation and thus play partly protective role in bacterial infection." (PMID 38022612, 2023). "Our study initially aimed at determining if neutrophil resistance to undergo Caspase-1-dependent pyroptosis can be overcome upon bacterial infection." (PMID 35849616, 2022). "The significantly delayed cell death and extensive cell-cell fusion observed in B. thailandensis-infected Casp8/Ripk3/Casp1/11−/− BMDMs suggested that bacterial infection is poorly controlled in these cells compared to WT." (PMID 34154417, 2021).
bacterial infection (continued). "In response to viral and bacterial infection these inflammasomes trigger caspase-1 activation and subsequently induce the release of mature pro-inflammatory interleukins such as IL-18, contributing to the immune response to pathogens." (PMID 32155831, 2020). "IEC shedding was found to be significantly enhanced upon bacterial infection in WT and Casp11−/− monolayers as compared to modest shedding in Casp1−/− and Casp1/11−/− cells." (PMID 32282854, 2020). "During bacterial infection, it has been demonstrated that the activation of caspase-1 by NLRP3 inflammasome inhibits the action of NADPH oxidase." (PMID 31781121, 2019). "Confocal imaging showed that caspase-1 activation occurred in the cells with the most bacterial infection and uptake of LL-37." (PMID 30978238, 2019). "In this regard, it is reported that caspase-1 and gasdermin-D mediate pyroptosis during bacterial infection." (PMID 30248149, 2018). "During bacterial infection, caspase-1 and caspase-11 are known to inhibit bacterial proliferation independent of pyroptosis." (PMID 30062052, 2018). "UBE2L3 depletion by caspase-1 occurs in macrophages and dendritic cells after canonical and non-canonical inflammasome activation by microbial or sterile signals and bacterial infection." (PMID 28147281, 2017). "We discuss the importance of caspase-1 and caspase-11 in host defense, and we examine the downstream consequences of inflammasome activation within the context of bacterial infections." (PMID 25879288, 2015). "This realization prompted a reassessment of the independent roles of caspase-1 and caspase-11 in bacterial infections." (PMID 25879288, 2015). "The NLRP3/caspase-1 inflammasome pathway plays an important role in cellular immune defence against bacterial infection; however, its function in human dental pulp tissue and human dental pulp fibroblasts remains poorly understood." (PMID 25684031, 2015). "Even so, much remains to be learned regarding the role of caspase-1 activation in the control of bacterial infection." (PMID 22558425, 2012). "L. monocytogenes infection triggers activation of caspase-1, and during some bacterial infections, caspase-7 can be a substrate of caspase-1." (PMID 22807671, 2012). "C. trachomatis infection at high MOIs can be detected by AIM2 in macrophages, which activates caspase-1 in cells upon bacterial infection but is also known to drive caspase-3-dependent apoptosis—a less inflammatory mode of cell death—in caspase-1-deficient cells." (PMID 39772728, 2025). "For instance, caspase-12 was shown to inhibit mucosal immunity to bacterial infection via suppression of the Nod-Rip2-NF-kB signaling pathway, as well as via inhibition of caspase-1 activation and subsequent IL-1β and IL-18 secretion, although the latter remains controversial." (PMID 41012634, 2025). "The reduced expression of these mediators suggests that caspase-1 may not only regulate inflammatory cytokine responses but also facilitate tissue repair during bacterial infections." (PMID 40137780, 2025). "Furthermore, it has been reported that the mRNA expression of inflammasome components (NLRP3, ASC, and caspase-1) varies in response to bacterial infections." (PMID 37834004, 2023). "NLRC4 responds to bacterial flagellin and a conserved type III secretion system (TTSS) rod component, recruits pro-caspase-1 to directly form NLRC4 inflammasome and involves in a variety of pathogenic bacterial infection, such as Salmonella, Shigella, Pseudomonas aeruginosa." (PMID 34513725, 2021). "Thus, caspase-1 independent release of IL-1β occurred during bacterial infection of macrophages and RIP1 activation was at least in one instance suppressive of this." (PMID 26659062, 2015). "Because cleavage by caspase-1 may reduce PO activity, the enzyme activity in the plasma was measured after bacterial infection." (PMID 24722332, 2014).
bacterial infection (continued). "Based on these results, we can reasonably infer that the inhibition of inflammasome activation by the caspase-1 inhibitor may weaken the protective effect of ATP against bacterial infection." (PMID 23717478, 2013). "While CASP1 inhibition may prove beneficial in terms of increasing inflammatory responses, it is ambiguous in terms of benefit for bacterial infections." (PMID 22432004, 2012). "We observed F. novicida colocalizing with mature caspase-1 in the livers of infected mice, which may represent the first time that the active inflammasome has been visualized during bacterial infection in vivo." (PMID 21698237, 2011). "In fact, upregulation of extracellular ATP has been observed in the context of bacterial infections and secretion of processed IL-1β Thus, prerequisites for caspase-1 activation and IL-1β processing/secretion in skin macrophages exposed to B. burgdorferi are likely in place." (PMID 20976193, 2010). "If proIL-1β expression is induced by LPS prior to bacterial infection or treatment with mycolactone, the resulting proIL-1β could be cleaved by activated caspase-1 and mature IL-1β could be readily released, along with the induction of necrotic cell death by mycolactone." (PMID 37910490, 2023). "Secreted CASP1 is a marker of inflammasome activation, which is consistent with our observed inflammatory responses, while secreted CASP3 has been linked with bacterial infection, with some pathogens capable of decreasing CASP3 activity, as we detected with Sp." (PMID 32847022, 2020). "Even though (a) IL-1β/IL-18 secretion might occur independently of pyroptosis and (b) caspase-1 or caspase-11 deletion is more severe than IL-1β/IL-18 ablation in some bacterial infections, usually cytokine release and cell death are overlapping events necessary for optimal host defense." (PMID 30459758, 2018). "However, it remains unclear whether caspase-1 was also activated by caspase-8, as observed in bacterial infections, by active caspases-3/7, which were previously shown to activate NLRP3-dependent inflammation upon TLR signaling, or independent activation of the NLRP3 inflammasome." (PMID 41173854, 2025). "The western-blot results showed that knockdown of β-catenin enhanced the cleavage of Caspase-1, IL-1β and GSDMD at indicated time points after pyogenic bacterial infection." (PMID 36068223, 2022). "Increased expression of caspase-1, secretion of IL-1β (facilitated by caspase-1), and increased substrate of GSDMD, are frequently reported in bacterial infection-related pyroptosis and sterile inflammation." (PMID 34360821, 2021). "In response to DNA in the cytoplasm in viral and bacterial infection, the sensor AIM2 recruits ASC and Casp1 to form the AIM2 inflammasome complex, which also leads to the autocleavage of Casp1 to generate Casp1 p10 and p20." (PMID 33613874, 2021). "In response to bacterial infection, the NLRP3 inflammasome would be assembled for the caspase-1 activation." (PMID 29184853, 2017). "Coincidentally, AT2 do not express Casp1, but are prone to Casp11-dependent pyroptosis during a bacterial infection." (PMID 40642082, 2025). "Following bacterial infection, caspase-1 activity increased in WT macrophages but not in Txnip KO macrophages." (PMID 31781121, 2019). "In any case, the susceptibility of GSDMD and other GSDM deficient mouse strains to infectious agents and its comparison to mice lacking caspase-1, caspase-11, IL-1β, and/or IL-18 remains to be established, especially in non-bacterial infection contexts." (PMID 30459758, 2018). "In addition, a pharmacological inhibitor, AC-YVAD-cho, which selectively inhibits the activation of Caspase-1, was used to reveal the role of NLRP3 inflammasome activation in protecting mice from bacterial infection." (PMID 23717478, 2013).
bacterial infection (continued). "Although the importance of Caspase-1, and its target, IL1-β, in PMN activation and antimicrobial functions are not fully appreciated in different physiological contexts, our prior studies demonstrated that inflammasome activation in PMNs occurs during bacterial infection." (PMID 36191054, 2022). "Importantly, we show that lung epithelial cells do not express inflammasomes components or caspase-1 suggesting that this cell type relies exclusively on caspase-11 for undergoing cell death in response to bacterial infection." (PMID 29791511, 2018). "Caspase-1, but not caspase-4, controls pyroptosis- and ubiquitin-independent proteasomal degradation of UBE2L3 upon canonical and non-canonical inflammasome activation by sterile danger signals and bacterial infection." (PMID 28147281, 2017). "In neutrophils, activation of canonical caspase-1 inflammasomes or non-canonical caspase-11 inflammasomes also triggers GSDMD-mediated pyroptotic death, which is essential for host protection from extracellular or intracellular and cytosolic bacterial infections." (PMID 38195694, 2024).
inflammation (42 papers, 2011 to 2025). Aberrant reaction of the microcirculation characterized by movement of fluid and leukocytes from the blood into extravascular tissues. "Together, these data suggest that TSLP-TSLPR signaling induces Bcl-xL up-regulation, which reduces cell apoptosis and bleomycin-induced airway inflammation caused by increased caspase-1 and caspase-3 activity in this setting." (PMID 32103153, 2020). "It has been reported that pulmonary exposure to SiO2 causes acute pulmonary inflammation in mice, which reaches a maximum at 24 h after the exposure, and that the pulmonary inflammation is mediated via caspase-1 inflammasome activation." (PMID 28399878, 2017). "Several genes that are involved in mucosal protection and immunity, such as Cxcl2 and IL-12A, retain levels of expression that are comparable to those observed in WT C57BL/6 mice and Lcn2, a gene that has been associated with gut inflammation, was detected at higher levels in Casp1−/− mice." (PMID 23977202, 2013). "Our in vivo experiments confirm that NLRP3 inflammasomes exacerbate endothelial inflammation and apoptosis through the caspase-1 pathway." (PMID 41323268, 2025). "Studies suggest that in HI and WMI models, microglia trigger severe brain inflammation via caspase-1-dependent pyroptosis, releasing IL-1β and IL-18, which impair OPC differentiation and maturation." (PMID 40254577, 2025). "A recent study has shown that LPS can activate the NLRP3/ASC/Caspase-1 signaling pathway, leading to renal inflammation and interstitial fibrosis." (PMID 39193336, 2024). "Consistent, treatment of silica-instilled mice with tetracycline significantly reduced pulmonary caspase-1 activation as well as IL-1β and IL-18 production, thereby ameliorating pulmonary inflammation and lung injury." (PMID 35130879, 2022). "It is reported that a selective inhibitor of the p38 MAPK signaling pathway, SB203580, suppresses the NLRP3/caspase-1-dependent pyroptosis in AMs, which results in the amelioration of lung inflammation." (PMID 35819638, 2022). "Blocking pyroptosis of macrophages by inhibiting the NLRP3 inflammasome or caspase-1 reduces silica-mediated pulmonary inflammation and fibrosis." (PMID 35819638, 2022). "In summary, current study suggests that tetracycline inhibits caspase-1 activation in response to silica and ameliorates silica-induced pulmonary inflammation including IL-1ß production, thereby reducing lung injury and fibrotic lung remodeling." (PMID 35130879, 2022). "To investigate the role of the NLRP3/caspase-1 pathway in a model of acute intestinal inflammation, we modified a previously established in vitro triple culture model of the healthy and inflamed intestine (Caco-2/HT29-MTX-E12/THP-1)." (PMID 35911682, 2022). "Studies have shown that NLRP3 knockout in nonalcoholic steatohepatitis (NASH) mice model inhibited the activation of NLRP3, ASC, and caspase-1 in liver and can significantly reduce liver inflammation in mice and prevent the development of the NASH disease." (PMID 33643422, 2021). "Recent studies have shown that PM2.5-induced pulmonary inflammation is associated with activation of NOD-like receptor protein 3 (NLRP3) and caspase-1 pathway, which can trigger cell pyroptosis." (PMID 34147136, 2021). "We have recently reported that SiO2 NPs strongly induce caspase-1 inflammasome activation and subsequent pulmonary inflammation in mice." (PMID 28399878, 2017). "In conclusion, here we unravel a detailed signaling pathway, where ozone-induced neutrophilic airway inflammation and IL-17A production are mediated through the mitochondrial ROS-caspase-1-IL-1 cascade." (PMID 26739627, 2016). "In this study, we demonstrate that sub-acute exposure to ozone induces a production of IL-17A and neutrophilic airway inflammation, which is mediated by a mechanism involving caspase-1-IL-1 cascade." (PMID 26739627, 2016).